INS (insulin)
Diseases named in the same sentence as INS in open-access papers (continued):
Sharing a sentence is not in itself a finding about the gene and the disease.
Insulin resistance (continued). "In three studies measuring insulin resistance, one study described a significantly lower resistance to insulin post-gastrectomy and two studies reported increased insulin requirements after patients commenced ADT." (PMID 28467470, 2017). "To investigate the relationship of secretome data to insulin sensitivity, we examined the content of diabetogenic lipids, i.e., diacylglycerols (DAGs), identified as key players in lipid-induced insulin resistance." (PMID 28885548, 2017). "Assessing this result, we assume that FABP4 enhances the process that β cells compensate insulin secretion against the insulin resistance in patients with T2DM." (PMID 28654680, 2017). "Surprisingly, fructose rapidly induced an insulin resistance as well as a reduced insulin sensitivity, respectively, shown with variations of HOMA 2-IR and ISI-gly." (PMID 28497040, 2017). "In other words, if peripheral insulin resistance is corrected, then probably insulin secreted by β cells is adequate to maintain normoglycemia." (PMID 28824543, 2017). "Serum 25OHD, fasting glucose, insulin and insulin resistance (HOMA-IR) were measured in early (12 weeks’ gestation) and late pregnancy (28 weeks’ gestation)." (PMID 28775759, 2017). "Insulin resistance (IR), an impaired biological response to insulin, is the pathological basis of T2DM." (PMID 29479370, 2017). "Studies have shown that insulin resistance is more severe and beta cell insulin production is elevated in African populations with normal glucose tolerance compared with European populations." (PMID 28144712, 2017). "This is highly possible since excessive exposure to insulin in vivo and in vitro can induce insulin resistance models with decreased pAkt and pGSK3βSer9 levels." (PMID 28282917, 2017). "ZAG levels were inversely correlated with body mass index (BMI), waist-to-hip ratio (WHR), the percentage of body fat, triglyceride (TG), fasting plasma glucose (FPG), fasting insulin, and homeostasis model assessment of insulin resistance (HOMA-IR)." (PMID 28352283, 2017). "This is characterised by increasing insulin secretion, which compensates for insulin resistance while keeping glucose values stable." (PMID 28409212, 2017). "In individuals with insulin resistance risk, HIIT improves insulin sensitivity, increases the maximum oxygen intake, decreases body mass and body fat percentage." (PMID 29270126, 2017). "Consistent with HFD-induced insulin resistance, insulin-dependent phosphorylation of IR and AKT was decreased in HFD-fed, ASO-ctrl-treated mice, compared with ND." (PMID 27884961, 2017). "These compounds along with anthocyanin rich extracts were found to be effective in ameliorating the insulin resistance condition and also increase insulin sensitivity, decrease body weight gain and accumulation of lipids." (PMID 29023424, 2017). "The identification and development of pharmacological insulin-sensitizers has led to promising ways to reduce insulin-resistance." (PMID 29222456, 2017). "Our study shows that circulating FABP4 concentrations are negatively correlated with both GDR, which is a marker of insulin resistance in skeletal muscle, and serum blood insulin levels (IRI) following a MTT in individuals with T2DM." (PMID 28654680, 2017). "The strong correlation between insulin sensitivity and intracellular TG content (i.e. liver and muscle tissues) has been well-established in human and animal studies of obesity-related insulin resistance and type 2 diabetes." (PMID 29163785, 2017). "M1 type macrophages are associated with inflammation and the development of impaired cellular response to insulin, so‐called insulin resistance." (PMID 28474500, 2017). "Their modulatory effect in insulin resistance appears to be mediated via targeting the various specific insulin signal transduction pathways of enzymes/receptors and also through general antioxidant and anti-inflammatory mechanisms." (PMID 29023424, 2017).
Insulin resistance (continued). "Although reduced insulin clearance and liver IDE expression has been associated with insulin resistance and the development of glucose intolerance, in early life, IDE KO mice showed higher plasma insulin concentration and improved glucose tolerance." (PMID 28951790, 2017). "Insulin resistance (IR) occurs when the insulin-sensitive tissues (mainly skeletal muscle, adipose tissue, and liver) lose their ability to respond properly to insulin, which has been assumed as a major pathophysiological feature of T2DM." (PMID 28883792, 2017). "Significant differences were also found in insulin resistance parameters including insulin level, HOMA-IR, and HOMA-β." (PMID 28716139, 2017). "The etiology of prediabetes is primarily skeletal muscle, liver, and/or adipose tissue insulin resistance that, in time, promotes oversecretion of insulin from the β-cell and results in pancreatic exhaustion that leads to severe hyperglycemia." (PMID 29387730, 2017). "The dysfunction of insulin signal transduction triggers insulin resistance; once this signal is weakened or disrupted, insulin resistance occurs." (PMID 28710412, 2017). "Human studies also showed that 8 weeks supplementation of Cosmos caudatus significantly improves insulin resistance and insulin sensitivity in type 2 diabetic patients." (PMID 28228098, 2017). "Insulin levels in girls were slightly lower than in boys, which is probably a reflection of early development of insulin resistance in boys resulting in many cardiovascular risks later in life." (PMID 28754153, 2017). "Although the reduction in insulin sensitivity in obese people is related to various molecular and cellular mechanisms, the pathogenesis of obesity-related insulin resistance is still unclear." (PMID 28367174, 2017). "Insulin resistance in the brain impairs insulin signaling, which can influence the regulation of food intake, body weight, reproduction, and learning and memory." (PMID 28162091, 2017). "Terpenoids extracted from Liriope platyphylla (belonging to Liliaceae) altered the expression of Glut1, Glut3, and key proteins in the insulin signaling pathway in the liver of ICR mice treated with high fructose diets to mitigate insulin resistance." (PMID 28146130, 2017). "The homeostasis model assessment estimate of insulin resistance (HOMA-IR) has been determined from serum insulin and glucose values." (PMID 28900377, 2017). "Twenty-five days’ treatment lowered serum glucose, insulin, leptin, and triglycerides, and reduced homeostasis model assessment-insulin resistance." (PMID 28360931, 2017). "Insulin resistance associated with PGMO, PE, and GDM results in foetoplacental vascular dysfunction and altered vascular reactivity to insulin." (PMID 29104874, 2017). "Dysfunction of normally insulin-sensitive adipose tissue has been repeatedly shown to be involved in important metabolic pathologies, such as insulin resistance, T2D, obesity and CVD63." (PMID 28496128, 2017). "We have previously shown that hepatic deletion of only p110α results in severe insulin resistance and impaired glucose tolerance, signifying that p110α is crucial for mediating insulin signaling." (PMID 29983910, 2017). "Treatment of obese diabetic rats with ML leaf extract significantly increased insulin sensitivity, with concomitant decrease in the level of insulin resistance." (PMID 28693595, 2017). "Intriguingly, we recently extended our research and determined that BPA exposure resulted in brain insulin resistance in mice, which demonstrates the disturbance in the insulin signaling pathways." (PMID 28790390, 2017). "Pro-inflammatory adipokines interfere with the insulin-signaling pathway of peripheral tissues and facilitate development of insulin resistance." (PMID 28538869, 2017). "For example, vitamin D has been suggested to stimulate insulin secretion and decrease insulin resistance and to also exert anti-cancer activity, including anti-proliferative and anti-inflammatory effects." (PMID 28134804, 2017).
Insulin resistance (continued). "Investigation of human obesity and insulin resistance has demonstrated a clear relation between the chronic activation of pro-inflammatory signaling pathways and decreased insulin sensitivity." (PMID 29387832, 2017). "Insulin stimulates tyrosine phosphorylation of insulin receptor signalling (IRS) proteins, which is a crucial event in mediating insulin action and is the primary signalling defect of systemic insulin resistance." (PMID 28435687, 2017). "Adipocytes are involved in the development of insulin resistance, resulting from the dysfunction of the insulin signaling pathway." (PMID 28846649, 2017). "Hyperinsulinemia concurrent with hyperglycemia, as biomarkers of insulin resistance, make this mouse a viable model to study mechanisms leading to increased insulin sensitivity." (PMID 28640904, 2017). "Collectively, these data strongly suggest that overproduction of SeP functions as a causal factor for hyperglycaemia in type 2 diabetes by inducing both insulin resistance and impaired insulin secretion, at least in rodents." (PMID 29162828, 2017). "HFD-fed rats showed a raise of 66, 170 and 75% in plasma glucose, insulin and insulin resistance, respectively, over their corresponding normal control rats, which was considerably reduced with piperonal supplementation in a dose-dependent manner." (PMID 29176994, 2017). "Surrogate indicators for insulin resistance and sensitivity, as well as pancreatic β-cell function, can be extrapolated from fasting blood glucose and insulin levels that are commonly included in population-based studies." (PMID 28253317, 2017). "The excessive influx of lipids can now reach the white adipose tissue, generating white adipose tissue (WAT) hypertrophy of it; the skeletal muscle, where it triggers insulin resistance; or the pancreas, inhibiting the production and secretion of insulin." (PMID 28425939, 2017). "Chickens are naturally hyperglycemic and insulin resistant; thus, the chicken is a potential model for studying human obesity, insulin resistance and type 2 diabetes." (PMID 28486516, 2017). "The increase in WC and TG level aggravated insulin resistance, which in turn increased insulin secretion to serve a compensatory function to maintain near-normal glucose tolerance." (PMID 28831093, 2017). "Cav‐1 knockout and Cav‐1‐targeted microRNA contribute to the development of insulin resistance by blocking insulin‐elicited tyrosine phosphorylation and activation of IRβ." (PMID 28514055, 2017). "The slightly decreased Akt phosphorylation after insulin injection in AT from anti-ANG2 antibody-treated mice further suggests that ANG-2 neutralization impairs insulin signaling and promotes insulin resistance." (PMID 28355132, 2017). "Both the Matsuda index and HOMA-IR showed that MODY3 participants had much greater insulin sensitivity (or lower insulin resistance) than T2D (P-values <0.05)." (PMID 28493909, 2017). "One animal study demonstrated that insulin resistance induced by a 12-week high fat diet (HFD) impaired osteoblastic insulin signaling, osteoblast proliferation, and osteoblast survival and resulted in osteoporosis of the jawbone in a mouse model." (PMID 28704413, 2017). "Macrophage infiltration is positively related to the size of adipocytes and coincides with the appearance of insulin resistance as macrophages alter the levels of insulin signalling molecules and GLUT4 and inhibit insulin action." (PMID 28827671, 2017). "Diabetes develops from insulin resistance, a relative insufficiency of insulin‐mediated decrease of blood glucose levels." (PMID 28474500, 2017). "Exposure to HFD provokes antiviral signaling and inflammatory response, but the consequence of insulin resistance attenuates insulin-mediated suppression of antiviral responses." (PMID 29254175, 2017). "Protease inhibitors, like nelfinavir, induce peripheral insulin resistance and with long-term use can impair insulin secretion." (PMID 28190636, 2017).
Insulin resistance (continued). "Gestational diabetes mellitus (GDM) is defined as hyperglycemia first detected during pregnancy, ultimately due to insufficient insulin production relative to the physiologic insulin resistance of pregnancy." (PMID 28577545, 2017). "As a result, the overall indices, oDI and ISSI-2, which allow compensating insulin secretion for the prevailing level of insulin resistance, decreased significantly from baseline to end-of-follow-up." (PMID 29053727, 2017). "The characteristic features of insulin resistance are hyperinsulinemia and impaired biologic response to insulin within target tissues." (PMID 28400351, 2017). "The glucocorticoid treatment induced an insulin resistance as shown by the simultaneous increases in both post prandial insulin and glucose levels when fed the casein protein meal." (PMID 29045496, 2017). "Several studies investigated the role of insulin resistance and impaired insulin signaling in the AD pathogenesis in brain and neuro-inflammation is mutual interaction between T2DM and AD." (PMID 28505155, 2017). "It is caused either due to insufficient insulin production from pancreatic beta cells (T1DM), or due to insulin resistance (T2DM)." (PMID 28837672, 2017). "The estrogen-deprived rats demonstrated several features of obese-insulin resistance as indicated by significantly increased levels of body weight, fasting plasma glucose and insulin, plasma cholesterol and HOMA index in NDO group." (PMID 28281660, 2017). "Although several tests exist to assess insulin resistance, the availability of new markers is highly needed, in the aim to achieve a more reliable assessment of insulin metabolism." (PMID 27473078, 2017). "On the other hand, controls who napped had higher levels of insulin and insulin resistance, and had lower eGFR." (PMID 29276708, 2017). "For all patients, mean insulin sensitivity was lowered (56% of normal), indicative of substantial insulin resistance." (PMID 28899393, 2017). "We examined blood glucose, insulin, homeostasis model assessment of insulin resistance (HOMA-IR), Leptin, body weight, epididymal fat, hepatic steatosis, Aβ burden, glial activation, and nesting behavior in HFSTZ-APP/PS1 mice." (PMID 29258283, 2017). "Insulin resistance (IR) is generally defined as a reduced ability of insulin to provoke metabolic responses, such as glucose uptake." (PMID 29091029, 2017). "In contrast, GK rats presented all the typical hallmarks of T2DM, such as insulin resistance, defective insulin production, fasting hyperglycemia/hyperinsulinemia and lipid plasma alteration." (PMID 29220408, 2017). "In vitro studies abound indicating that proinflammatory cytokines are able to inhibit insulin signalling and thus promote the development of insulin resistance in fat cells and muscle cells." (PMID 26661101, 2016). "During the development of T2D, β-cells initially compensate for insulin resistance by increasing the amount of insulin in circulation." (PMID 26916443, 2016). "The frank hyperglycemia in the presence of comparable amount of plasma insulin concentrations together with reduced K-value indicated the persistence of insulin resistance in HFD-fed and STZ treated diabetic control rats." (PMID 27313954, 2016). "In conclusion, this study demonstrated that adiposity (BMI, WC, WHtR and BF%) and fitness (physical fitness score) correlate with fasting insulin and HOMA-IR, with gender, BMI and WC being significant predictors for high fasting insulin and insulin resistance." (PMID 27824069, 2016). "This strongly suggests that, even in insulin resistance, the enhancement of sodium reabsorption via NBCe1 by insulin is preserved." (PMID 27247938, 2016). "SITT is a more accurate method for the evaluation of in vivo insulin sensitivity compared to the homeostasis model assessment of insulin resistance in humans." (PMID 27051457, 2016).
Insulin resistance (continued). "Fasting blood glucose and serum insulin levels were measured and followed insulin resistance index (HOMA-IR) was evaluated according to the homeostasis model assessment." (PMID 26807509, 2016). "While increased IMCL storage per se can be seen in healthy, insulin-sensitive athletes, it has also been shown that IMCL deposition in sedentary subjects can be associated with insulin resistance." (PMID 27649157, 2016). "In summary, the present ISN model permits to investigate the insulin signaling network in the insulin resistance states and in cancer, focusing on the role played by Akt phosphorylated at Ser473 and by the mTOR complexes, as well as on the drug effects." (PMID 27149630, 2016). "Bouzakri and Zierath reported that TNF-α leads to insulin resistance by directly targeting muscle insulin signaling." (PMID 27878229, 2016). "Insulin resistance is a dysmetabolic condition in which a greater amount of insulin is required to exert a physiological cellular response." (PMID 27725832, 2016). "Thiazolidinediones (TZDs) is types of insulin sensitizing drugs used for type 2 diabetes treatments and it ameliorate insulin resistance by promoting the adipocyte proliferation and differentiation through up-regulation of PPAR-γ in the adipocyte." (PMID 27604997, 2016). "Despite decreased AKT2 mRNA at week 2 (−28.6%, P = 0.002) and increased PTPN1 mRNA at week 24 (+50.3%, P = 0.016) suggesting insulin resistance, clinical insulin sensitivity [by homeostasis model assessment (HOMA-IR)] was unchanged." (PMID 27516476, 2016). "These hormones, which are counter-regulatory to insulin, contribute to increased insulin resistance in the early postpartum period." (PMID 27570545, 2016). "CEACAM1 is a molecule that induces insulin clearance and reduces fatty acid synthesis in liver in the presence of insulin resistance, hepatic steatosis and visceral obesity." (PMID 27657051, 2016). "Beyond the antioxidant effects, there was a reduction of insulin resistance, a decrease in endogenous insulin hypersecretion and a reduced need for exogenous insulin administration." (PMID 27527163, 2016). "The authors showed that the oral administration of CTB-APSL fusion protein can effectively reduce the levels of blood glucose and glycosylated hemoglobin, promoting insulin secretion and improving insulin resistance." (PMID 27916864, 2016). "The pathophysiological hallmarks of T2D in mammals are an impaired response of peripheral tissues to insulin (insulin resistance) and impaired insulin secretion from pancreatic β-cells." (PMID 27053133, 2016). "Intervention studies investigating the beneficial effect of low-GI diets on insulin sensitivity are limited to obese/overweight subjects with insulin resistance." (PMID 27973411, 2016). "It has been postulated that peripheral insulin resistance induces a compensatory hypersecretion of insulin by the pancreas." (PMID 27613445, 2016). "In contrast, insulin resistance refers to the decreased response of peripheral tissues to insulin signaling." (PMID 27053133, 2016). "The reduction of DCI results in the decreased availability of inositol phosphoglycan that is a second messenger of insulin and thus contributing to the onset of insulin resistance." (PMID 27688754, 2016). "Treatments (pre- and post-) successfully reduced the insulin resistance and increased the insulin level." (PMID 28036014, 2016). "Enhanced expression of FOXO1 downstream target gene PDK4 gene is also observed in high fat and obese animal models of insulin resistance, which adversely regulate insulin actions." (PMID 26956801, 2016). "In patients with high insulin resistance and nutrition at goal, “rebound hyperglycemia” was noted after the insulin analog was rapidly metabolized." (PMID 26819233, 2016). "This suggested that despite insulin resistance, the mice still had enough pancreatic islet β cell reserve to be able to mount a glucoregulatory insulin response after a glucose challenge." (PMID 27261415, 2016).